WNT1 (Wnt family member 1)
Diseases named in the same sentence as WNT1 in open-access papers (continued):
Sharing a sentence is not in itself a finding about the gene and the disease.
cancer (continued). "For example, reduction in WNT1 expression induces apoptosis of many human cancer cells, including non-small cell lung cancer, breast cancer, mesothelioma, sarcoma, and colorectal cancer cells." (PMID 23094073, 2012). "This phenotype was similar to that seen with RNAi knockdown of Wnt1, indicating that Wnt1 is important for cancer cell survival." (PMID 24212796, 2011). "Based on the increased epithelial cellularity of the KO-glands and published data implicating RARα in anti-cancer activity, we expected that the RARα1/KO mice crossed with the MMTV-wnt1 mice will be more susceptible to wnt1-induced tumorigenesis." (PMID 20923554, 2010). "Recently, it has been reported that Wnt-1/β-catenin signaling inhibits apoptosis in several cancers." (PMID 15913453, 2005). "Neoplasms with a pure luminal phenotype (simple carcinomas) were identified in all transgenic models of mammary carcinogenesis with the notable exception of Wnt1-induced carcinomas that had a constitutively complex phenotype." (PMID 15535849, 2004). "As expected, all Wnt1-induced carcinomas and spontaneous type P tumors displayed myoepithelial differentiation." (PMID 15535849, 2004). "The main pathways of methylome biomarkers were associated with calcium signalling (CACNA1E, RYR2, RYR3), cancer pathways (DCC, RASSF1, WNT1, CTNNA2), multiple neurodegenerative diseases (WNT1, DNAI1, RYR2, RYR3), immune system disorders and cell adhesion (HLA-DRA, HLA-DRB1, HLA-DRB5)." (PMID 40524349, 2025). "The WNT1 pathway is significantly upregulated in all cancer cells (p < 0.001), suggesting that Brentuximab impacts Wnt signaling, which is known for its role in cell proliferation and cancer progression." (PMID 39805861, 2025). "WNT10B is directly downstream of the cancer pathway gene WNT1 (~8 kb away)." (PMID 37756103, 2023). "Its levels of signaling did not correlate with the cell death marker, which might be because Wnt-1 protects cells from apoptosis only when expressed in exceedingly high numbers as in cancer cells." (PMID 33673194, 2021). "Wnt1, which was originally named Int-1, was first identified in mouse cancer cells." (PMID 33041875, 2020). "WNT1 has been reported to be a direct target of miR-34a in several types of cancer." (PMID 32301035, 2020). "CRC cells expressing Wnt1 are resistant to cancer chemotherapy, and Wnt1 could inhibit the apoptosis by activating β-catenin/TCF transcription." (PMID 32923386, 2020). "We are working to further define the Wnt1/b-catenin-driven molecular mechanisms that inhibit chemokine production by cDCs, hoping to reveal novel insights into the complex regulation of cross-priming and open new avenues for optimizing cancer immunotherapies." (PMID 30926812, 2019). "This could be related to Wnt1 overexpression being particularly frequent in LUAD compared to other types of cancer." (PMID 30926812, 2019). "Taken together the decreased TCR stimulation, low granzyme B secretion and impaired cytotoxicity of in vitro and in vivo primed T cells by intratumoral Wnt1-cDCs, these data collectively show that Wnt1 suppresses the ability of cDCs to cross-prime T cytotoxic cells against cancer-specific antigens." (PMID 30926812, 2019). "Positive expression of wnt1 was observed mainly in the cytoplasm of cancer cells." (PMID 28218651, 2017). "Moreover, compound SJ26 inhibited the WNT1-mediated downstream signaling pathway and suppressed migration activity of cancer cells." (PMID 27626678, 2016). "and the overall survival is lower in patients with Wnt1-positive cancer." (PMID 27626678, 2016). "Moreover, it has been reported that miR-148a suppressed EMT and cancer stem cells-like properties by targeting Wnt1 (wingless-type MMTV integration site family member 1) and Met, leading to inhibition of metastasis of HCC." (PMID 25760076, 2015).
cancer (continued). "PR target genes include soluble factors known to modify cancer stem cells (WNT1 and RANKL)." (PMID 24552158, 2014). "Therefore, inhibition of cancer cell proliferation and attachment is required to suppress Wnt-1/Frizzled/LRP." (PMID 23982808, 2013). "To identify the paracrine factors responsible for T47D carcinoma cell growth stimulation we treated the co-cultures with neutralizing antibodies to eleven factors implicated in stroma-carcinoma interactions (FGF-2, HB-EGF, Heparanase-1, HGF, IGF-1, IGF-2, MT1-MMP, PDGF, SDF-1, TGF-β1, and Wnt-1)." (PMID 23056402, 2012). "In addition, we demonstrated that both a monoclonal anti-Wnt-1 antibody and Wnt-1 siRNA induced apoptosis in human cancer cells." (PMID 15913453, 2005). "Wnt proteins, including Wnt-1, have been shown to be expressed in several cancers." (PMID 15913453, 2005). "We have asked whether functional Id2 expression is necessary for Wnt induced mammary hyperplasia, side branching, and cancer, by generating mice expressing a Wnt1 transgene in an Id2 mutant background." (PMID 15601467, 2004). "We have asked therefore whether functional Id2 expression is necessary for Wnt induced mammary hyperplasia, side branching and cancer, by generating mice expressing a Wnt1 transgene in an Id2 mutant background." (PMID 15601467, 2004). "In addition, the pathology pathway concept predicts that Myc-, Hras-, and Neu-induced carcinomas should share similar pathways, distinct from those of Wnt1-induced carcinomas." (PMID 15535849, 2004). "Additionally, FJX1 expression was significantly and positively correlated with immunosuppressive genes (TGFB1 and IL-10), chemokines (CCR1 and CCR5), chemokines receptors (CCL2 and CXCL5), and immunosuppressive pathway-related genes (TFGB1 and WNT1), in most TCGA cancers." (PMID 37324001, 2023). "Additionally, HSP family members, along with tumor necrosis factor (TNF) ligand family cytokines and Wnt-1 protein involved in Wnt/β-catenin signaling pathway, key players in redox regulation and cancer development, were among the retrieved proteins though at lower significance." (PMID 36670957, 2022). "Indeed, there was a striking decrease in numbers and activation status of intratumoral OVA-specific T cytotoxic cells upon inoculation of ovalbumin-expressing Wnt1-LLC cells, further suggesting that Wnt1 impacts T cell responses against cancer-specific antigens." (PMID 30926812, 2019). "In addition, overexpression of miRNA-148a inhibited Wnt1 protein expression in cancer cells." (PMID 28199399, 2017). "However, cancer cells cannot operate the Axin/APC/GSK-3β complex by overexpression of Wnt-1." (PMID 23982808, 2013). "Therefore, these particular antibodies may only be useful in cancers that are specifically driven by Wnt1 or Wnt3a." (PMID 24212796, 2011). "These target genes, including IGFBP1, WNT1, WNT10B, TGFB1, PCK1, and SLC2A3, are critical for cancer cell proliferation and metastasis." (PMID 42311859, 2026). "INO-5401 consists of genes that are active in human cancers (hTERT, PMSA, and WNT1) and are considered effective targets for the immune system of individuals who have had cancer or for those at an increased risk of developing cancer." (PMID 40243654, 2025). "The downregulation of Wnt1 expression and its downstream factors, including β-Catenin/HIF-1α-mediated glycolysis, indicates the intricate mechanism by which XHP disrupts cancer cell metabolism and progression." (PMID 38994113, 2024). "In this study, we assessed TET1 and Wnt1 expression in 5-azacytidine-treated HT29 cells, a demethylating agent commonly used in cancer therapy." (PMID 39495308, 2024).
cancer (continued). "Mechanistically, in premalignant lesions, CCL2 produced by cancer cells and myeloid cells attracted CD206+/Tie2+ macrophages and induced Wnt-1 upregulation, which in turn downregulated E-cadherin junctions in HER2+ early cancer cells." (PMID 37208442, 2023). "Expression of miR-148a is likewise significantly downregulated in primary cancer tissues of NSCLC patients compared to their adjacent normal lung tissues, and negatively correlates with the expression of Wnt1, a direct target of miRNA-148a." (PMID 33585487, 2021). "Having shown that Wnt1 is a marker of adaptive immune tolerance in human LUAD, we sought to investigate its relevance to other types of cancers." (PMID 30926812, 2019). "In accordance, when all mice were challenged with OVA-LLC cancer cells, tumors grew at much slower rates in the control mice, suggesting that impaired differentiation of OTI cells to memory cells is a Wnt1-driven mechanism of adoptive T cell therapy failure." (PMID 30926812, 2019). "We found that induction of Wnt1 increased NADPH production, cancer cell survival and clonogenic capacity under metabolic stress while knockdown of Snail rescued Wnt-induced metabolic reprogramming." (PMID 28176759, 2017). "As in Wnt1-transfected HEK293T cells, Z86 efficiently inhibited the Topflash activity in both cancer cell lines in a dose-dependent manner after 24 h of treatment." (PMID 27551464, 2015). "Similar to Snail genes that are resistant to apoptosis, invasion and migration of cancer cells promote the epithelial-mesenchymal transition (EMT) and induce increased Snail levels in the nucleus through upregulation of Wnt-1 signaling." (PMID 23982808, 2013). "Genome-wide methylation-associated biomarkers were involved in the pathways of neurodegeneration-multiple diseases (13%), cancer-related pathways (DCC, RASSF1, WNT1, CTNNA2; 13%), and Hippo, calcium signalling, cell adhesion and immune system-related pathways (all 10%)." (PMID 40524349, 2025). "• Exertion of anticancer effects through 3 major pathways: apoptosis (BIRC3, BIRC5, caspase-8, caspase-9, and PARP1), transcriptional dysregulation in cancer (CDKN1A, CDKN1B, MMP9, MYC, JUN, and RELA), and cancer progression (caspase-3, CCND1, CTNNB1, VEGFA, and Wnt-1)." (PMID 39181121, 2025). "Considering the significance of Wnt/β-catenin pathway for the link between precancerous lesions and cancer, this study further analyzed whether C1s affected the proliferation of ESCC via the Wnt1/β-catenin pathway." (PMID 39071493, 2024). "Similarly, our study also predicts target genes like E2F1, WNT1, RALA, and PTEN that reveal their involvement in cancer progression." (PMID 38741808, 2024). "CCL2 could recruit CD206hi macrophages and increase Wnt-1 production from those cells, which led to decreased levels of E-cadherin in the HER2+ cancer cells, resulting in the early dissemination of cancer cells." (PMID 36674955, 2023). "In addition, in pre-malignant lesions, CCL2 produced by cancer cells and myeloid cells attracts CD206+/Tie2+ macrophages and induces Wnt-1 upregulation that, in response, downregulates E-cadherin junctions in the HER2+ early cancer cells." (PMID 35892884, 2022). "Interestingly, Wnt1 is downregulated in response to Salmonella infection in CRC and this inhibits cancer cell invasion and migration." (PMID 33585487, 2021). "The three clusters generated contained genes or proteins involved in apoptosis (BIRC3, BIRC5, PARP1, CASP8, and CASP9), transcriptional dysregulation in cancer (CDKN1B, RELA, CDKN1A, MYC, JUN, and MMP9), and cancer progression (CCND1, CASP3, CTNNB1, WNT1, and VEGFA) pathways." (PMID 34836311, 2021).
cancer (continued). "Mechanistically, miR-148a appears to suppress the extravasation process of cancer cells, likely by targeting two genes WNT1 and NRP1 in a cell non-autonomous manner." (PMID 26967387, 2016). "Until now, no study has been carried out to clarify the role of Wnt1 and β-catenin activation with special respect to clinicopathology, overall and cancer-specific survival." (PMID 23708097, 2013). "Therefore, alterations of the Wnt1/β-catenin axis in clear cell RCC (ccRCC) were examined with regard to clinicopathology, overall survival (OS) and cancer specific survival (CSS)." (PMID 23708097, 2013). "In addition to the well-studied canonical WNT1, dysregulation of several WNT ligands induces aberrant WNT/β-catenin signaling in different cancers or tumors, with inconsistency of typical classification." (PMID 23094073, 2012). "In previous studies, we have demonstrated its efficacy in induction of apoptosis in human cancer cell lines and shown that the antibody lacks general toxicity in cells lacking the Wnt-1 protein." (PMID 15913453, 2005). "In addition, small interfering RNAs against EMT transcription factors or key EMT-related genes have been used to inhibit cancer EMT, including Zinc-finger E-box-binding 1 (ZEB1), twist family bHLH transcription factor 1 (TWIST1), Nogo-B receptor and Wnt family member 1 (WNT1)." (PMID 36915713, 2023). "In addition, BCP regulated AKT, Wnt1, and beta-catenin expression, showing that CB2R stimulation may decrease cancer cell proliferation by modulating Wnt/β-catenin signaling." (PMID 34830893, 2021). "Moreover, to further confirm the specificity of Wnt1 in breast cancer metastasis, we treated cells with Wnt1 ligand with or without Wnt1 knockdown and then evaluated cancer cell metastasis." (PMID 26202299, 2015). "Expression of c-myc and cyclin D did not properly adjust Wnt-1 signal transduction in cancer cells." (PMID 23982808, 2013). "Moreover, we speculate that canonical and non-canonical WNT pathways could control ovarian carcinogenesis, because β-catenin is absent in cancer cell nuclei, despite a strong WNT-1 expression." (PMID 24499657, 2014). "However, these genes did not operate in cancer cells by stimulated Wnt-1 and mutant Axin, and LRP combined with Wnt-1 activation." (PMID 23982808, 2013).
adenocarcinoma (10 papers, 2004 to 2025). A common cancer characterized by the presence of malignant glandular cells. "Both AAV-P– and Lenti-PIK3CAH1047R–induced tumors on the Wnt1-transgenic background are adenocarcinoma, but there are also remarkable histological differences." (PMID 37172086, 2023). "The transcriptional activation of the Wnt1 (int-1) gene was firstly proved to be the initiating step in mammary gland hyperplasia and adenocarcinomas in mice." (PMID 32923386, 2020). "Wnt1 regulates cellular differentiation and proliferation of the mammary epithelium, and Wnt1 up-regulation in the mammary gland has been shown to induce mammary hyperplasia and adenocarcinoma." (PMID 23469146, 2013). "In mice, expression of Wnt1 and stabilized β-catenin (ΔN89β-catenin) under the control of the mouse mammary tumor virus LTR (MMTV) induces precocious mammary development and adenocarcinoma formation." (PMID 19225568, 2009). "Wnt1 was originally discovered as an oncogene activated by mouse mammary tumor virus (MMTV), and mice engineered to express either Wnt1 or an activated form of β-catenin from the MMTV-LTR develop mammary hyperplasia and adenocarcinoma." (PMID 20126544, 2010).
infection (6 papers, 2004 to 2020). The state of being infected such as from the introduction of a foreign agent such as serum, vaccine, antigenic substance or organism. "To investigate whether HCV core protein alters Wnt-1 expression, we measured the levels of Wnt-1 mRNAs and protein after the transient infection of Ad-HCV core into the HepG2 cells." (PMID 24416131, 2014). "In HFDPCs, the increased levels of Rip1, Wnt1, and Wnt4 were only detected at day 1 after DENV-2 infection, but decreased at days 2 and 33 in comparison to the mock infection." (PMID 32121148, 2020). "Long-term infection of DENV-2 downregulated the expression of hair growth regulatory factors, such as Rip1, Wnt1, and Wnt4." (PMID 32121148, 2020). "qRT-PCR in WS1 showed that Rip1, Wnt1, Wnt4, and cMyc expressions were inducted by DENV-2 (MOI 1, 5, and 10) after one and/or two days of infection, but decreased at day 33 post-infection, particularly in the MOI 5 and 10 infected WS1 cells." (PMID 32121148, 2020). "The infected mice exhibited increased mRNA levels of canonical (Wnt1, Wnt2, Wnt3, and Wnt3a) and noncanonical (Wnt5a) Wnt molecules, receptors (Fz1 and Fz5) and the Wnt signalling target gene Sox9 in hepatocytes at 6 and 12 weeks post-infection." (PMID 28331224, 2017).
cardiovascular disease (4 papers, 2013 to 2023). "In this study, we demonstrated that Wnt1 was able of saving c-kit+ CSCs from apoptosis induced by oxidative stress (H2O2), suggesting that Wnt1 may have a therapeutic use in the prevention and the treatment of cardiovascular diseases." (PMID 23533594, 2013).
skeletal dysplasia (2 papers, 2014 to 2024). Any Mendelian diseases that affects growth and development of the skeleton. "Type XV OI is a moderate to severe form of skeletal dysplasia caused by WNT1 variants." (PMID 39126373, 2024).
inflammation (1 paper, 2012). Aberrant reaction of the microcirculation characterized by movement of fluid and leukocytes from the blood into extravascular tissues. "In contrast, the role of WNT signaling in lung inflammation is largely unexplored, although the canonical pathway activator WNT-1 is implicated in lung inflammation by being linked to stimulation of pro-MMP3 transcription." (PMID 22846383, 2012).
neurodegenerative disease (1 paper, 2025). A disorder of the central nervous system characterized by gradual and progressive loss of neural tissue and neurologic function. "The canonical signaling pathway activated by Wnt1, the Wnt/β-catenin signaling cascade, also plays a crucial protective role in neurodegenerative diseases." (PMID 40025242, 2025).
renal diseases (1 paper, 2021). "Wnt1 canonical signaling activates fibroblasts directly or via interaction with TGF-β, and therefore has become a topic of considerable importance related to fibrosis in various renal diseases." (PMID 34122087, 2021).
WNT1 also shares sentences with these, for which no sentence is quoted: oral cancer (4 papers); thyroid cancer (3); triple-negative breast carcinoma (3); astrocytoma (2); bladder cancer (2); dyslipidemia (2); esophageal cancer (2); gastric adenocarcinoma (2); idiopathic juvenile osteoporosis (2); medulloblastoma (2); oral squamous cell carcinoma (2); wasting syndrome (2); ankyloglossia (1); Anorexia (1); autism spectrum disorder (1); autoimmune disease (1); autosomal dominant retinitis pigmentosa (1); basal cell carcinoma (1); Blepharophimosis (1); cardiac ischemia (1); cardiomyopathy (1); Cerebral ischemia (1); cervical tumor (1); Charcot arthropathy (1); cholangiocarcinoma (1); cholelithiasis (1); Clear Cell Renal Cell Carcinoma (1); cognitive deficits (1); colitis (1); colorectal tumors (1).
A further 57 diseases each share a sentence with WNT1 in 1 paper.